IL15 (interleukin 15)
Diseases named in the same sentence as IL15 in open-access papers (continued):
Sharing a sentence is not in itself a finding about the gene and the disease.
tumor (continued). "Subsequently, other groups have also described the expansion of CD56bright NK cells with anti-tumor activities, and associated this with interleukin 15 (IL-15) treatment." (PMID 31277459, 2019). "Positive associations of ANGPTL-4 with IL-10 and IL-15 and IL-15 in the tumor and the mesenteric adipose tissue were observed in WSC group." (PMID 31741709, 2019). "On the other hand, in weight stable patients, who had a low ANGPTL-4 levels in plasma and tumor, it was observed an association of this protein to IL-10 and IL-15, anti-inflammatory and anti-tumorigenic factor." (PMID 31741709, 2019). "The human E2F-1 promoter was operably linked to E1A in SG400-E2F1 and SG400-E2F/IL-15 to restrict expression of E1A to Rb pathway-defective tumor cells." (PMID 31278126, 2019). "For example, in a breast tumor model, early control of tumor progression is critically dependent on innate lymphocytes, as IL-15 deficient animals, which lack group 1 innate lymphocytes showed accelerated tumor growth." (PMID 30298068, 2018). "Here, our data demonstrate a slight reduction of tumor growth after vaccination with the plasmid encoding TH compared to the IL-15 control plasmid." (PMID 30452438, 2018). "NK cells are key mediators of antibody-dependent cell cytotoxicity (ADCC); in mice, the increase of NK cell number following CIV IL-15 was associated with increased ADCC of anti-tumor antibodies and their efficacy." (PMID 30400822, 2018). "In summary, our study indicates that IL-15 elicits a distinct tumor-promoting effect from tumor-associated myeloid cells." (PMID 29255466, 2017). "Based on these different HTM models, we investigated the immune response, the importance of FcgRIIIa polymorphism, and the adaptation processes of the tumor cells during trastuzumab and IL-15 treatment." (PMID 27835865, 2017). "Accumulated evidences have shown that IL-15 was significantly associated with a decreased incidence of tumor recurrence and a prolonged overall survival, including HCC." (PMID 29162948, 2017). "IL-7 and IL-15 mediated TCR sensitization enables T cell responses to self-antigens such as tumor associated antigens." (PMID 28477011, 2017). "Inflammation has been reported to increase tumor formation and loss of IL-15 promoted tumor development in the Granzyme B Tax model." (PMID 29050201, 2017). "Results from these arrays suggest that IL-15 affected the expression of MMPs and TIMPs associated with tumor metastasis." (PMID 28379958, 2017). "This suggests that IL-15 causes inflammation and changes in stroma that can promote decreased tumor cell proliferation." (PMID 28379958, 2017). "Much research has focused on the ability of IL-15 to inhibiting tumor cell proliferation in vivo, but the potential mechanism underlying the antitumor activity of IL-15 also involves up-regulating NK cell and CTL activity." (PMID 29296227, 2017). "Overall we elucidated the importance of a human immune response for an efficient trastuzumab treatment in HTM, an association of tumor cell phenotype to treatment response, and the power and peril of IL-15 as an immunotherapeutic add-on in cancer." (PMID 27835865, 2017). "NK cells cultured with IL-15 showed an upregulation of NKp30, which is associated with an increase anti-tumor activity and with an improved maturation of immature DCs." (PMID 28824651, 2017). "These very latest functional experiments are an elegant evidence for the role of IL15 gene in anti-tumor response, and are in line with our results on the association of IL15 polymorphism with MRD-status." (PMID 27427275, 2016). "We demonstrate that IL-15 expression in the tumour-bearing brains of EE mice is associated with in situ accumulation of activated CD45+/CD69+ leukocytes, and specifically of NK cells, that are markedly increased in comparison with SE mice." (PMID 25818172, 2015). "Recently, it has been reported that IL-12 can induce a rapid release of interleukin-15 (IL-15) by tumor-associated and tumor-infiltrating macrophages." (PMID 25997501, 2015).
tumor (continued). "Significant associations between poor tumor differentation and high concentrations of GM-CSF, IL-15 and IL-8 were observed." (PMID 26498838, 2015). "The most pronounced effect of IL-15 loss on tumor-associated cytokine protein was on IL-6, which was reduced an average of 7-fold in IL-15−/− Tax tumors." (PMID 24416335, 2014). "Using Tax-LUC mice as a model in which IL-15 is capable of promoting both cancer and cancer immunity, we sought to determine the effect of IL-15 loss on tumor growth in vivo." (PMID 24416335, 2014). "Elevated levels of tumor-cell associated IL-1α protein were present in formalin-fixed paraffin embedded sections of IL-15−/− tumors." (PMID 24416335, 2014). "It is also noteworthy that, unlike IL-1β, the elevated levels of IL-1α in normal skin keratinocytes was sufficiently high in this assay to mask any quantifiable effect of IL-15 on IL-1α protein expression within the underlying tumor." (PMID 24416335, 2014). "Further analysis of these tumors revealed effects of IL-15 loss on both the malignant population and the tumor infiltrating immune cells and led us to conclude that the net effect of IL-15 in this cancer model is promotion of tumor immunity." (PMID 24416335, 2014). "We chose to administer IL-15 pre-chemotherapy given the risk of metastatic failure for dogs while receiving chemotherapy, but the interplay of chemotherapy and immunotherapy on anti-tumor responses is a key question moving forward." (PMID 41209004, 2025). "However, IL-15 causes systemic toxicity and is ineffective in head and neck cancer and lung cancer, promoting tumor progression." (PMID 40469178, 2025). "Also, toll-like receptor (TLR) activation on macrophages and dendritic cells by damage-associated molecular patterns (DAMPs) released by dying tumor cells induces IL-15 expression." (PMID 40299429, 2025). "Indeed, adequate intratumoral IL-15 levels within the TME are essential for optimal antitumor efficacy, with diminished local IL-15 production closely linked to increased tumor relapse rates and decreased patient survival outcomes." (PMID 41455698, 2025). "Moreover, a biomimetic nanovaccine co-delivering IL-15 and tumor-associated antigens selectively targets IL-15 to antigen-specific CTLs, reducing off-target toxicity and extending the cytokine's half-life by 8.2-fold." (PMID 40083941, 2025). "Feeder cell systems, such as EBV-transformed lymphoblastoid cell lines and K562 erythroleukemia cells engineered to express membrane-bound IL-15 and 4-1BBL, have been shown to promote the expansion of NK cells with partial specificity for tumor-associated antigens." (PMID 40498022, 2025). "Presence of TLS in HGSOC tumors associated with B cell maturation & cytotoxic tumor-specific T cell activation & proliferation.Copy-number loss of IL15 & CXCL10 may limit TLS formation in HGSOC." (PMID 40475770, 2025). "A high expression level of IL-15 in tumor cells was associated with a high TNM stage." (PMID 38637902, 2024). "Similarly, pre-clinical data demonstrated that NK CARs expressing IL-15 and IL-15/IL-15Rα were associated with improved anti-tumor activity and persistence." (PMID 38817602, 2024). "IL-15 was linked to the C-terminal Fc domain with the intention to likely preserve high-affinity binding to PD-L1, favored by the opposite sites of binding, on either tumor or immune cells of the TME." (PMID 39204319, 2024). "In other words, NK cells possess the ability to activate interleukin-15 (IL-15) to mitigate tumor mutational burden in SCLC models, indicating that targeting NK cells within the SCLC microenvironment may provoke a specific response." (PMID 38957470, 2024). "Additionally, in patients IL-15 stimulation showed improved efficacy of CD19-CAR NK cells by overcoming partly tumor-induced loss of metabolic fitness." (PMID 38331849, 2024). "The loss of NK cell functionality after tumor entry could be blocked through enhanced IL-15 signaling, leading to improved control of tumor growth." (PMID 38267402, 2024).
tumor (continued). "Consistent with this, IL-15 therapy can prevent tumor dissemination caused by JAK2 inhibitors." (PMID 38672681, 2024). "These challenges can be addressed through efficient delivery of mRNA-encoding IL-15 to the tumor." (PMID 39543114, 2024). "Our results suggest that the differential actions of intracellular and extracellular IL-15 on tumor cells might be caused by their distinctive modes of engaging the IL-15 receptor." (PMID 38637902, 2024). "The loss of NK cell functions within the tumor could be prevented through enhanced IL-15 signaling, which pushed intratumoral NK cell differentiation towards a hybrid state defined by high CD49a expression, but also enhanced effector functions." (PMID 38267402, 2024). "However, tumor cells and tumor-associated macrophages express the receptor IL-15R or its α-subunit, which reduces IL-15 efficacy, giving rise to tumor resistance." (PMID 37296860, 2023). "Although IL-15 possesses antitumor functions by activating natural killer and T-cell responses, a pathogenic role in hematological malignancies has been reported, with overexpression correlated to tumor development." (PMID 37932837, 2023). "The biomimetic nanovaccine is composed of cytomembrane vesicles, derived from genetically engineered dendritic cells (DC), onto which IL-15/IL-15 receptor α (IL-15Rα), tumor-associated antigenic (TAA) peptide/MHC-I, and relevant costimulatory molecules are simultaneously anchored." (PMID 37875481, 2023). "Indeed, recombinant human IL-15 and sIL-15/IL-15Rα, employed alone or in association with other therapies, cause efficient tumor regession in several experimental tumor models." (PMID 37334356, 2023). "One of the reasons for curtailed maximum expansion in patient-derived γδT cells could be the dull responsiveness of IL-15Rα to IL-15 resulting from the long-term deficiency in IL-15 within the tumor microenvironment." (PMID 35351861, 2022). "Additionally, it was recently reported that IL-15 renders NK cells less susceptible to the oxidative stress induced by myeloid cells in the tumor microenvironment." (PMID 36713398, 2022). "We have previously shown that ICE®/tumor-antigen associated cross-link-experienced healthy donor-derived NK cells are triggered to phenotypic changes boosting proliferation and cytotoxic capacity in response cytokines, such as IL-2 and IL-15." (PMID 35225870, 2022). "In tumor, IL-15 was associated with lymphocyte infiltration in the micro-environment, and we might speculate that TRIM22 mediated this process and further exploration awaits." (PMID 35371994, 2022). "Intriguingly, in these S100a8-cre-Il15fl/flPyMT mice, the loss of cancer-cell derived IL-15 resulted in reduced αβILTCK recruitment into the tumour tissue and impaired cancer immunosurveillance, with accelerated tumour growth in comparison to wild-type controls." (PMID 35768418, 2022). "In transplanted and spontaneous tumor models, IL-15-deficiency and the subsequent reduction in T and NK cell numbers leads to accelerated tumor development, suggesting that IL-15 plays a critical role during early anti-tumor responses." (PMID 36032129, 2022). "Moreover, IL-15 deficiency in the tumor epithelium greatly diminished the amount of ILC1ls and accelerated PyMT tumor growth." (PMID 36372017, 2022). "These suggest that CAR cells may be used as vehicles to deliver the cytokines locally to the tumor microenvironment where it can provide the most benefit while avoiding the potential toxicities associated with high systemic IL-15 levels." (PMID 36172388, 2022). "Taken together, the loss of IL-7, IL-15, and IL-18 may be playing a role in the decreased numbers of lymphocytes in the tumor microenvironment, which supports a protumorigenic environment." (PMID 33290281, 2021). "Moreover, it has been demonstrated that upregulated IL-15 expression also exists in monocytes, macrophages, and tumor-associated neutrophils in inflammatory environments." (PMID 33815365, 2021).
tumor (continued). "Knocking out the interleukin IL15 also caused a similar acceleration in tumor onset." (PMID 33235291, 2021). "Furthermore, it is reported that tumor remission by anti-CD19 CAR associated high serum IL-15 levels in cancer therapy." (PMID 33752225, 2021). "A measles virus Schwarz vaccine strain (MeVac) vector encoding an IL-15 superagonist increased NK infiltration into tumours in vivo, and MeVac expression of an IL-12 fusion protein was found to promote immune activation and anti-tumour effects." (PMID 34888493, 2021). "Meanwhile, continuous IL-15 exposure to NK cells could result in arrested cell cycle, diminished viability, reduced tumor cytolytic activity and metabolic deficiency, and this exhaustion status could be reversed by mTOR inhibitor." (PMID 33266177, 2020). "Also, plasma ANGPTL-4 level was positively associated with IL-10 and IL-15 contents in tumor and with IL-15 content in mesenteric adipose tissue." (PMID 31741709, 2019). "Also, the downregulation of the anti-inflammatory factors as IL-10 and IL-15 contribute for the development of the tumor and loss of body mass." (PMID 31741709, 2019). "Interestingly, we determined that IL-15 caused an increased influx of inflammatory cells to the tumor site, and an increase in adipocytes." (PMID 28379958, 2017). "Similarly, IL-15 enhanced the antitumor activity of trastuzumab, yet causing fatal side effects in a humanized tumor mice model." (PMID 29181007, 2017). "We also demonstrate that IL-15 causes an increase in neutrophil infiltration in the tumor tissue." (PMID 28379958, 2017). "PCR array: Genes associated with tumor metastasis differentially expressed by IL-15 in vivo." (PMID 28379958, 2017). "Additionally, the antitumor effect of IL15 has been well established in several mouse tumor models, with an IL15 deficiency possibly resulting in an acceleration of tumor growth." (PMID 27438147, 2016). "Based on our initial observation that IL-15 overexpression correlated with tumor growth we hypothesized that loss of IL-15 would impede tumor onset or growth." (PMID 24416335, 2014). "Moreover, prophylactic vaccination with 102 pfu of IL-2 or IL-15 encoding vectors reduced the tumor burden, whereas the same dose of Flt3L vector completely prevented tumor growth." (PMID 24312302, 2013). "Indeed, these molecules are composed of two single-chain variable fragments (scFvs), one engaging the CD16 on NK cells and one engaging a tumor-associated antigen, connected by small linkers and IL-15, a cytokine that stimulates the expansion of NK cells, and their ADCC functions." (PMID 33921413, 2021). "Studies have established that cytokine-induced memory-like (CIML) NK cells, generated through in vitro induction via the cytokines IL-12, IL-15, and IL-18, have demonstrated long-term tumor cell persistence and cytotoxicity in preclinical and clinical trials." (PMID 41498114, 2026). "The present study indicates that Anti-MICB-CAR has been successfully expressed in primary natural killer (NK) cells and secretes free Anti-MICB-scFv and interleukin-15 (IL-15), demonstrating strong tumor-killing ability." (PMID 41516373, 2026). "Anti-MICB-scFv and IL-15 in the supernatant of Anti-MICB-CAR-NK cells co-treated tumor cells with NK cells also promoted tumor cell killing compared to NK." (PMID 41516373, 2026). "The tumor microenvironment can also be modulated by cytokines and/or cellular vaccines such as modified dendritic cells that overproduce IL-12, IL-15/IL-15Rα, and IL-18." (PMID 41846923, 2026). "Co-administration of B7-H6M4-LC21 with IL-15/IL-15Rα sushi fusion achieved synergistic tumor inhibition, outperforming T cell-based strategies and emphasizing NK cells’ unique capacity to overcome stromal immunosuppression." (PMID 40873574, 2025). "Neutrophil polarization into a pro-tumour phenotype can be induced by IL-15 in mice, leading to production of a range of cytokines and chemokines." (PMID 41503139, 2025).
tumor (continued). "Tumor clearances were achieved in both IL-21 and IL-15 NK cells, with the highest proportions of cancer cell deaths induced by IL-21 NK cell cytotoxicity." (PMID 40027823, 2025). "Our previous studies have shown that the addition of IL-7 and IL-15 significantly improves the anti-tumor effect of CAR-T cells." (PMID 41450878, 2025). "In summary, we provide evidence that IL-15 complexes injected intratumorally reach the tumor-draining lymph node, where they can activate and mobilize immune cells, including CD8+ T cells." (PMID 41373645, 2025). "CISH knockout reprograms iPSC-derived NK cell metabolism, increases their sensitivity to IL-15 signaling, and improves in vivo persistence in tumor models." (PMID 40315330, 2025). "Here, we report the design of novel trifunctional tumor-directed antibody-cytokine fusion protein formats combining IL-15 with IL-21 or IL-7." (PMID 40370435, 2025). "It is likely that the endogenous IL-15 expression in CAR iNK cells helped counteract TGF-β signaling–induced suppression on iNK cells in the tumor." (PMID 40315330, 2025). "These unique immunostimulatory properties position IL-15 as a potential therapeutic candidate for enhancing anti-tumor immunity in canine MGTs." (PMID 40552079, 2025). "Cytokines such as VEGF, IL‐1β, PDGF, and FGF promote tumor formation, and IFNs, IL‐2, IL‐12, and IL‐15 inhibit tumor growth." (PMID 40356340, 2025). "In this study, we assessed the efficacy of combining CD25-targeted NIR-PIT, intratumoral IL-15, and anti-PD-1 mAb in highly-immunogenic and poorly-immunogenic tumor models." (PMID 41410776, 2025). "Interleukin-15 (IL-15) is a cytokine adjuvant that prolongs anti-tumor activity via activation of natural killer (NK) cells and CD8+ T cells." (PMID 40584631, 2025). "Nanocarriers can deliver cytokines like IL-15 and IL-21, checkpoint inhibitors, or gene-editing tools directly to NK cells or the tumor microenvironment." (PMID 41375063, 2025). "Kurz, Hirsch analyzed the tumor microenvironment in mice following aerobic exercise and found that it promoted the mobilization and accumulation of interleukin-15 (IL-15) and enhanced the infiltrative capacity of CD8+ T cells." (PMID 40700217, 2025). "The combination regimen (B7-H6M4-LC21 + IL-15 fusion) significantly enhanced tumor suppression versus monotherapies (achieved 76.1% ± 14.8% tumor growth inhibition; p < 0.05) without significant weight changes at therapeutic doses." (PMID 40873574, 2025). "We observed an increase in IL-15 expression and IL-15 had an inhibitory effect on tumor development via the NK cells." (PMID 40431182, 2025). "Recent clinical trials have demonstrated that expanding and activating autologous NK cells in vitro, especially when combined with cytokines like interleukin-15 (IL-15), significantly boosts their anti-tumor effectiveness." (PMID 40308592, 2025). "Encapsulating IL-12, IL-15, or IL-21 in nanoparticles allows cytokine release at the tumor site, enhancing NK cell proliferation and cytotoxicity, while reducing cytokine toxicity." (PMID 40917849, 2025). "Like the prophylactic efficacy, the therapeutic B16-LX/IL(15 + 7) vaccine significantly inhibited B16-F10 tumor growth compared to the B16-LX/RFP vaccine, demonstrating the antitumor role of dual cytokines." (PMID 40957993, 2025). "Our strategy addresses this by pre-inducing IL-15 expression in EcN, with surface-tethered, protease-cleavable IL-15 ensuring tumor-specific release." (PMID 40532661, 2025). "“Armored” CARs, such as CD28-CD3ζ-IL-15, further enhance cytokine production and sustain NK cell functionality in the tumor microenvironment (TME)." (PMID 41462483, 2025). "By upregulating NKG2D receptor expression and activating immune cells, IL-2 and IL-15 enhance the antitumor response in LNs, potentially improving local immune interventions and aiding in tumor control." (PMID 40636453, 2025).